TREX1 (three prime repair exonuclease 1)
Diseases named in the same sentence as TREX1 in open-access papers (continued):
Sharing a sentence is not in itself a finding about the gene and the disease.
tumor (65 papers, 2012 to 2025). "Co-deletion of TREX1 and 3p was present in ≥ 60% of all cases of TREX1 loss in 28 out of 32 TCGA tumor categories." (PMID 40581636, 2025). "PCAWG tumor samples frequently had TREX1 copy number loss (predominantly a loss of one copy) or a gain from 1 to up to 7 additional copies." (PMID 40581636, 2025). "The loss or inactivation of TREX1 in cancer cells restricts tumor growth and potentiates checkpoint inhibition of the adaptive immune response." (PMID 40581636, 2025). "Collectively, these results suggest that TREX1 expression is closely linked to changes in immune activity, proliferative capacity, and extracellular matrix dynamics within the tumor microenvironment." (PMID 41346575, 2025). "Collectively, these findings suggest the potential of a TREX1 exonuclease inhibitor to work in combination with agents that generate cytosolic DNA to enhance the acquisition of the anti-tumor immunity widely associated with STING pathway activation." (PMID 39178223, 2024). "Together, these data indicate that TREX1 loss activates a tumor intrinsic innate immune response, probably caused by an aberrant accumulation of chemotherapy-derived cytoplasmic DNAs, which lead to the decreased growth rate of drug-resistant cells." (PMID 39177280, 2024). "The study recorded the presence of an ER membrane-associated exonuclease, TREX1, in the deformed nucleus of tumor cells." (PMID 36899842, 2023). "TREX1 and the cGAS-STING DNA-sensing pathway have also been implicated in the tumor microenvironment, where TREX1 is proposed to degrade tumor-derived DNA that would otherwise activate cGAS-STING." (PMID 33868310, 2021). "If the second functional allele were lost in a tumor, TREX1 sequence variants that follow a recessive pattern of inheritance in the germline may potentially have tumor inhibiting roles." (PMID 40581636, 2025). "Since multiple reports suggested that TREX1 has a protumorigenic effect and contributes to cancer resistance to therapy, the presence of TREX1 variants in tumor samples may have important clinical implications." (PMID 40581636, 2025). "However, despite the potential advantage of TREX1 amplification, the number of tumor samples in TCGA with TREX1 loss was 3.6 times higher than the number of samples with TREX1 copy number gain." (PMID 40581636, 2025). "Finally, loss of TREX1 in THP1 tumor cells increased tumor cell-derived Type-I IFN mRNA induction and the activation of DCs in response to the DNA damaging agent PBD SG-3199." (PMID 39178223, 2024). "Indeed, TREX1-deficiency in mouse tumor models has been demonstrated to elicit a strong anti-tumor immune response lending further support to the potential efficacy ofTREX1 inhibitors in the treatment of malignant disease." (PMID 39178223, 2024). "The TREX1-mediated DNA damage again promoted tumor growth and invasion by leading aberrant invasiveness in the tumor cells; the nuclear instability caused by altered expression of NE proteins is required for tumor aggressiveness in different types of cancer." (PMID 36899842, 2023). "Additionally, reports have shown that treating cancerous cells in vitro using UV-light, or different genotoxic anti-tumor agents is linked to the elevation of TREX1, and TREX1 siRNA knockdown initiates tumor cell deaths post-treatment." (PMID 34519260, 2021). "On the contrary, Trex1 knockdown in the tumor increased tumor infiltration of CD4+ T cells, CD8+ T cells, NK cells, and DCs, and decreased MDSCs." (PMID 41117130, 2025). "The IHC results revealed that TREX1 protein was localized in the cytoplasm of tumor cells, as indicated by brown-yellow staining, which was considered positive, whereas blue staining denoted negative expression." (PMID 41346575, 2025).
tumor (continued). "We found that Rfwd3 overexpression significantly promoted tumor growth, while Trex1 knockdown significantly inhibited tumor growth, compared to control cell‐triggered tumors in the mice." (PMID 41117130, 2025). "TREX1 is a radiation-driven upstream regulator of anti-tumor immunity that guides patient radiation dose selection." (PMID 39759116, 2025). "RFWD3 inhibited cGAS‐STING signaling by stabilizing TREX1 and degrading dsDNA, leading to the accumulation of MDSCs and suppression of anti‐tumor immunity." (PMID 41117130, 2025). "High levels of TREX1 in tumor cells can lead to decreased activation of the cGAS-STING pathway, allowing cancer cells to avoid detection and destruction by the immune system." (PMID 38881902, 2024). "Based on these reported findings, pharmacologic inhibition of TREX1 activity in tumor cells is expected to generate an increase in Type-I IFN secretion (and consequently, ISG stimulation) similar to that observed with STING agonists." (PMID 39178223, 2024). "Depletion of TREX1 contributes to the derepression of tumor-intrinsic innate immune response by accelerating the accumulation of cytosolic dsDNA derived from DNA damage and leading to a cGAS-STING pathway activation." (PMID 39177280, 2024). "In a separate study, direct microRNA targeting of TREX1 restored the immunogenicity of tumor cells and increased the secretion of proinflammatory factors into the tumor microenviroment." (PMID 39178223, 2024). "The percentage of infiltrating CD8+ T cells and the level of IFN-β expression were both raised by 10Gy carbon ion irradiation in the irradiated side tumor, although PD-L1 and TREX1 expression levels were also elevated." (PMID 38495488, 2024). "Together, these results suggest that targeting TREX1 is a promising strategy to induce a tumor-intrinsic innate immune response in drug-resistant SCLC by derepressing dsDNA-cGAS-STING pathway activation." (PMID 39177280, 2024). "Taken together, these data suggest that targeting TREX1 in chemoresistant SCLC cells has the potential to increase tumor cell immunogenicity capable of evoking CD8 T-cell activation." (PMID 39177280, 2024). "Consistent with previous results in human SCLC specimens, TREX1 expression was higher in the PDX sample derived from a posttreatment tumor, at protein and mRNA levels, which further suggests that TREX1 is induced after chemotherapy treatment in human SCLC." (PMID 39177280, 2024). "For comparison, tumor cells can be optimally stimulated to produce IFN and prime tumor-specific CD8+ T-cells at a low dose given below the threshold of Trex1 induction." (PMID 37122745, 2023). "When the radiation is delivered at a high dose, induced Trex1 degrades the accumulated cytoplasmic DNA in irradiated tumor cells, which precludes the activation of cGAS-STING-IFN signaling and dampens immune responses." (PMID 37122745, 2023). "TREX1 and cGAS-STING have been proposed to function in the tumor microenvironment, where TREX1 is believed to degrade tumor-derived DNA that would otherwise stimulate the cGAS-STING pathway and elicit antitumor immunity." (PMID 33868310, 2021). "Direct immune cell phagocytosis of tumor cells or exosome shuttling of tumor-derived DNA are possible, and the abundance of tumor-derived DNA correlates with tumor-intrinsic TREX1 expression." (PMID 33868310, 2021). "By inactivating Trex1 in tumor cells, the IFN I response induced by irradiation is increased, as well as the antitumor immune response." (PMID 34249754, 2021). "Upregulation of TREX1 following lethal irradiation of tumor cells was recently reported to prevent cGAS-STING mediated IFN-I production in tumor cells and tumor infiltrating DCs." (PMID 33717156, 2021). "A dose-dependent effect of DNA-damaging agents on TREX1 expression has been demonstrated, and showed that TREX1 degrades damaged DNA from drug-treated tumor cells." (PMID 33868310, 2021).
tumor (continued). "We showed that the inhibition of endothelial TREX1 through miR-103 and siRNA decreased angiogenesis and tumor growth." (PMID 34503262, 2021). "We observed similar functional consequences in murine models both in a neonatal ocular angiogenesis model and in the tumor vasculature with miR targeting of TREX1." (PMID 34503262, 2021). "The expression of TREX1 depends on the drug dosage treatment; hence, it is being overexpressed to suppress the tumor." (PMID 34519260, 2021). "Determination of mRNA expression in tumor tissues through RT-qPCR also confirmed significant downregulation of TREX1 mRNA in tumor tissues compared to the adjacent control tissues." (PMID 34519260, 2021). "The authors demonstrated that the threshold governing Trex1 activation varies according to the histological type of the tumor and needed to be carefully defined to sensitize the tumor to ICPi." (PMID 32707692, 2020). "TREX1 levels were upregulated exclusively in HPV-positive tumor cell lines and in PHK expressing HPV16 oncogenes." (PMID 30674977, 2019). "Wilson and co-workers have recently shown that miR-103 negative regulation of its target gene TREX1 reprograms the tumor microenvironment." (PMID 30674977, 2019). "We demonstrated that TREX1 silencing greatly affects tumor cells clonogenic and anchorage independent growth potential." (PMID 30674977, 2019). "In contrast, radiation given in repeated doses below the dose threshold for Trex1 induction optimally stimulates the cancer cells to produce IFNβ, required to recruit to the tumour and activate Batf3-dependent dendritic cells (DCs)." (PMID 28598415, 2017). "Here we report the results of our studies that identify the DNA exonuclease Trex1 as an upstream regulator of radiation-induced anti-tumour immunity, and show that Trex1 expression is dependent on the radiation dose." (PMID 28598415, 2017). "Doxycycline-mediated induction of Trex1 completely abrogated the development of tumour-specific CD8 T cell responses in draining lymph nodes, and the complete regression of irradiated tumours as well as abscopal responses were lost." (PMID 28598415, 2017). "Here the authors show that radiation induced miR-103 downregulates TREX1 in endothelial cells, decreases angiogenesis and leads to the secretion of proinflammatory mediators that reduce tumour growth." (PMID 27886180, 2016). "Mechanistically, miR-103 regulation of its target gene TREX1 in endothelial cells governs the secretion of pro-inflammatory cytokines into the tumour microenvironment." (PMID 27886180, 2016). "Taken together, our data identifies miR-103 regulation of TREX1 as a potent modulator of the tumour microenvironment." (PMID 27886180, 2016). "Prevalence of different TREX1 sequence and copy number variants was variable among TCGA and PCAWG samples from different tumor histologies, suggesting potential tumor-specific differences in the impact of TREX1 alterations." (PMID 40581636, 2025). "In addition, siRNA-mediated knockdown of the key gene TREX1 was performed in PC-3 cells, and EdU and Transwell assays were conducted to assess its effects on tumor cell proliferation, migration, and invasion." (PMID 41346575, 2025). "However, Rfwd3‐triggered decrease in CD4+ T cells, CD8+ T cells, NK cells, and DCs, and increase in MDSCs were suppressed by Trex1 knockdown, suggesting that RFWD3‐induced pro‐tumor immune suppression depends on TREX1." (PMID 41117130, 2025). "Additionally, three different nonsynonymous substitutions at position 23 were reported in TCGA and COSMIC for different tumor categories, suggesting possible protumorigenic effects of certain TREX1 changes." (PMID 40581636, 2025). "However, TCGA samples from different tumor histologies frequently lost one (shallow deletion), or, less frequently, both copies (deep deletion) of TREX1, or gained one (CNA gain) or more (amplification) additional gene copies." (PMID 40581636, 2025).
tumor (continued). "However, Rfwd3‐promoted tumor growth was markedly inhibited by Trex1 knockdown, suggesting that RFWD3‐induced tumor progression was at least partially mediated by TREX1." (PMID 41117130, 2025). "TREX1 gain also co-occurred with 3q gain in about 56% of samples, suggesting that TREX1 gain tends to occur within the context of larger chromosome 3 region amplification in specific tumor categories." (PMID 40581636, 2025). "PCAWG data confirmed TREX1 copy number changes in many tumor samples from a variety of histologies." (PMID 40581636, 2025). "It was discovered that down-regulating TREX1 might reduce tumor growth, trigger tumor cell death, and improve the sensitivity of certain radiation." (PMID 38495488, 2024). "Collectively, these data suggest that TREX1 depletion in chemoresistant SCLC cells contributes to the induction of a tumor intrinsic innate immune response by activating the cGAS-STING pathway, which senses chemotherapy-derived dsDNA aberrantly accumulated in the cytoplasm." (PMID 39177280, 2024). "Moreover, TREX1 is capable of degrading tumor-derived DNA in the cytoplasm, thereby compromising the IFN-dependent antitumor immunity induced by the cGAS-STING pathway." (PMID 38877472, 2024). "TREX1 inhibitors are expected to enhance tumor immunogenicity under a variety of therapeutic approaches, and may well function to overcome immunosuppressive effects of otherwise efficacious radiation therapy." (PMID 39178223, 2024). "However, Scr and sgTrex1 tumors were spontaneously rejected and we were unable to use this model to investigate the impact of TREX1 deletion on tumor growth and immune infiltration." (PMID 39177280, 2024). "Targeting TREX1 might enhance the effectiveness of immunotherapies by increasing the immune system’s ability to recognize and destroy tumor cells through the activation of the cGAS-STING pathway." (PMID 38881902, 2024). "Strong anti-tumor effects may also be possible with TREX1 inhibitor monotherapy in tumors with intrinsic chromosomal instability." (PMID 39178223, 2024). "For example, downregulation of TREX1 expression in tumor cells may elevate DNA accumulation, ribosomal collisions, and translational stress, thereby augmenting cGAS-dependent DNA recognition." (PMID 39420203, 2024). "Consequently, inhibition of TREX1 exonuclease activity is considered a potential immunotherapeutic strategy to restore antitumor immunity by reducing the degradation of tumor-derived DNA." (PMID 38877472, 2024). "TREX1 was mainly expressed on SCLC tumor cells which are positive for Cytokeratin and EpCAM." (PMID 39177280, 2024). "However, exposing tumor to a single high radiation dose (> 12–18 Gy) activates the deoxyribonucleic acid (DNA) exonuclease TREX1, preventing irradiated tumor cells from releasing IFN-β, and impairing the increased immunogenicity induced by radiotherapy." (PMID 37234164, 2023). "Depending on the type of tumour, TREX1 expression is upregulated or downregulated." (PMID 35883600, 2022). "However, the cytosolic DNA is degraded by three-prime repair exonuclease 1 (Trex1), which is activated by stresses such as high-dose ionizing radiation to mitigate the cytosolic DNA-induced anti-tumor immunity." (PMID 36230769, 2022). "Finally, TREX1 locates to micronuclei, degrading DNA when their membranes break, preventing its cytoplasmic sensing and supporting the chromosomal instability of tumours." (PMID 35883600, 2022). "Thus, it is possible that cGAS-STING stimulation contributes to antitumor immunity in both tumor and host immune cells indicating that TREX1, cGAS, and STING are candidate targets to modulate antitumor immunity." (PMID 33868310, 2021).
tumor (continued). "Additionally, TREX1 functions to degrade DNA in dying cells and inhibition of TREX1 in tumor cells should potentiate the innate immune anti-tumor effect as these cells die during treatment." (PMID 33868310, 2021). "TREX1 plays an upstream regulatory role in anti-tumor response mediated by radiation." (PMID 34519260, 2021). "TREX1 expression is initiated at a sufficient level for degrading DNA, which can accumulate in the cytosolic region of the treated tumor cell, precluding interferon (IFN-1) pathway activation induced through cyclic GMP-AMP (cGAMP) synthase (cGAs) and the associated downstream adaptor STING." (PMID 34519260, 2021). "In addition, TREX1 inhibits the transfer of dsDNA from irradiated tumor cells to dendritic cells (DCs) via tumor-derived exosomes, resulting in dampened cGAS/STING activation and IFN-β production in DCs." (PMID 33888558, 2021). "In a mouse model inoculated with tumor cells on the bilateral flank, the experimental data showed the local irradiation group knocked down the expression of Trex1 and the administration of anti-CTLA-4 restored the ability of abscopal effect induction, in contrast to the Trex1 upregulated group." (PMID 32992835, 2020). "Besides, our functional analyses suggest that TREX1 upregulation is important for tumor cells survival, tumorigenic potential and tumor establishment/progression." (PMID 30674977, 2019). "Thus, tumour-expressed Trex1 is an attractive target for interventions to improve in situ vaccination by radiotherapy and by other DNA damaging agents." (PMID 28598415, 2017). "Moreover, Trex1 knockdown in TSA cells in the irradiated tumour restored the ability of radiation used at 20 Gy with anti-CTLA4 to induce abscopal responses." (PMID 28598415, 2017). "Similarly, induction of Trex1 completely abrogated the regression of irradiated tumours as well as abscopal responses in mice treated with 8GyX3 and anti-PD-1." (PMID 28598415, 2017). "The present study has suggested that TREX1 gene may be related to the immunity of tumor and lupus erythematosus and the clinical outcome of cancer." (PMID 27881153, 2016). "Similarly 4T1 tumours treated with our EC targeted miR-103 had significant downregulation of TREX1 staining in the tumour endothelium." (PMID 27886180, 2016). "Although TREX1 functional loss in normal cells is associated with negative outcomes, increased TREX1 expression in tumor cells with inherent genetic instability may promote disease progression by limiting the acquisition of anti-tumor immunity." (PMID 39178223, 2024). "To further investigate TREX1-mediated regulation of tumor intrinsic innate immune responses in chemoresistant SCLC, we next asked whether a type I IFN response was induced after TREX1 depletion by measuring secretion of IFNβ protein in the conditioned media of sgTREX1 and Scr cells." (PMID 39177280, 2024). "Sequential delivery of sub-lethal doses of irradiation prevented TREX1 upregulation in tumor cells and allowed the activation of anti-tumor immune responses in an IFN-I-dependent manner, indicating that TREX1 may act as a rheostat to control radiation-induced tumor-derived immunostimulatory DNA." (PMID 33717156, 2021). "Despite reported methylation differences between the cell lines and primary tumor data and the lack of patient specimens in our analysis, associations identified in our study using cell line data, including those for TREX1, suggest novel therapeutic targets for potential clinical use." (PMID 32586373, 2020). "Thus, to ensure an optimal anti-tumor responses, short-course fractionated RT may need to be employed in part to prevent Trex1 induction leading to optimal sensing of the cytosolic DNA produced by RT." (PMID 30692991, 2018). "The dose threshold for Trex1 induction in primary human tumours may differ." (PMID 28598415, 2017).